CD69 (CD69 molecule)
Diseases named in the same sentence as CD69 in open-access papers (continued):
Sharing a sentence is not in itself a finding about the gene and the disease.
tumor (continued). "In both tumor models, IFNAR blockade delayed NK cell activation as measured by CD69 expression." (PMID 39196934, 2024). "Similarly, CD69 was expressed on 62.6% (± 2.94) and 32.1% (± 13.52) of hYP218 CAR T cells isolated from the tumour and spleen tissue, respectively." (PMID 39548594, 2024). "Also, a TRM-like cluster (CD69+CD103+) was detected, which was preferentially found in tumour (cluster 5)." (PMID 38986249, 2024). "Moreover, BG/OVA@EcN exhibited the strongest ability to promote tumor infiltration of the activated IFN‐γ+CD8+ T and CD69+CD8+ T cells, as well as the activated CD69+CD4+ T cells, while decreasing the numbers of Tregs (Foxp3+CD25+CD4+CD3+CD45+ cells)." (PMID 38009498, 2024). "To elucidate the underlying mechanisms associated with the improved therapeutic outcomes of DTIC/Epacasome-2, we then systemically investigated the NKG2D+(receptor), CD69+, IFN-γ+, Granzyme B+ or perforin+ NK and CD8+ T cells respectively, in tumours using flow cytometry." (PMID 37945606, 2023). "Expression of CD69, a marker for tissue-resident lymphocytes, was more frequently expressed toward the tumor center on CD16− NK cells and CD8+ T cells and in a similar but non-significant trend on CD4+ T cells, while nearly all ILCs expressed CD69 at all locations studied." (PMID 37448786, 2023). "To activate the adaptive immune response to tumors, we detected the expression of CD11c, MHC II, CD86, CD4, CD8, and CD69 in mouse transplanted tumors by IHC and studied the infiltration and activation of DCs and CD4+ T, and CD8+ T cells in the tumor microenvironment after (−)-Guaiol intervention." (PMID 36441354, 2023). "Zimmer et al106 found that MAIT cell frequency was reduced in tumor tissue compared with nontumor tissue in patients with cholangiocarcinoma, but tumor-infiltrating MAIT cells expressed high levels of the tissue-resident markers CD69 and CD103." (PMID 36584816, 2023). "This enrichment could potentially augment the tumor infiltration of CD4 + lymphocytes, alongside activated subsets of CD4 cells expressing KI67 + and CD69 + markers throughout the course of radiation therapy." (PMID 38033576, 2023). "Notably, the expression level of CD69 and KLRG1 were significantly reduced in the spleen, blood and tumor of TKO animals, indicating that these cells are less activated compared to those in WT controls." (PMID 37520575, 2023). "In the tumor-draining lymph nodes, mice treated with CpG-conjugated EVs also showed a higher CD8/Treg ratio and an increased number of CD69+ CD8+ T cells and memory-phenotype CD8+ T cells, in comparison with mice treated with EV alone or the mixture of EV and CpG." (PMID 38052869, 2023). "T/P-induced senescence in combination with GCV-mediated SMA+ fibroblast depletion led to significantly decreased tumor growth and increased infiltration of NK and CD4+ and CD8+ T cells and their expression of activation (CD69, Sca-1) and cytotoxicity (GZMB) markers compared to T/P treatment alone." (PMID 37142692, 2023). "In the untreated tumor, half of all T cells belonged to the exhausted CD8+ T cell cluster, characterized by expression of residence and checkpoint molecules such as PD-1, TIGIT, CTLA-4, LAG-3, CD69, and CD103." (PMID 37209684, 2023). "After tumour stimulation in vivo, these tumour‐infiltrating Rag2−/−‐OT1‐iT cells exhibited the typical effector cytotoxic T cells phenotype: CD44high CD62Llow CD69+ CD25+, whereas the splenic Rag2−/−‐OT1‐iT cells showed the memory phenotype (CD44high CD62Lhigh CD69− CD25−)." (PMID 36592612, 2023). "However, Foxp3UP CD8 T cell in the tumor exhibited a more activated and differentiated phenotype with higher expression of CD43 (130-kD), CD69, CD39, and KLRG1." (PMID 36045586, 2023).
tumor (continued). "Using this coculture model, we found that incubation with CMTM6-knockout tumor cells significantly reduced the expression of T cell activation markers (CD137 and CD69) and T cell effector cytokines (IL-2 and TNFα) compared to wild-type and CMTM6-reconstituted tumor cells." (PMID 37683639, 2023). "We first examined CD69 expression across different cell types and found that it was expressed almost exclusively on immune cells and not on tumor cells or CNS resident cells." (PMID 37426447, 2023). "Additionally, they showed that active CD8+ T cells infiltrated the tumor tissue with an increase in CD8+:CD4+ ratio and expression of CD69 suggesting recent infiltration and cytotoxic activity." (PMID 37245011, 2023). "In addition, lung leukocytes from CpG-NP-Tag had a more significant percentage activated (CD69+CD44hi phenotype) and produced more IFN-γ following ex vivo restimulation with viable 4T1 tumor cells and NP-Tag, respectively." (PMID 36839766, 2023). "Activation markers CD25 and CD69 were upregulated on CD4+ T cells in the presence of PDL1-BiTE/tumor, rather than PBLs/tumor." (PMID 39282109, 2023). "Coculture of NK cells with both PA tumor cells did not alter the expression of NKp46, NKp30, CD69, or CD16." (PMID 36451048, 2023). "Moreover, flow cytometry analysis showed that the percentages of tumor-infiltrating CD3+ T cells and CD69-positive CD8+ T cells were significantly increased after NPTyr-C9AP treatment." (PMID 37031188, 2023). "R848@M2pep-MPsAFP significantly increased the numbers of CD4+ T cells, activated CD4+CD69+ T cells, CD8+ T cells, proliferated CD8+ T cells and activated CD8+CD69+ T cells, CD8+IFNγ+ T cells and CD8+GzmB+ T cells in tumor tissues compared with free R848, R848@MPs, R848@M2pep-MPs and R848@MPsAFP." (PMID 37704614, 2023). "Notably, in addition to these treatment effects in the targeted tumor, we also found increased abundance of central memory T cells (CD44+CD62L+), CD44+ effector T cells and CD69+ activated T cells among CD4+ and CD8+ T cells in the TDLNs in PIC + RT group 45." (PMID 35999216, 2022). "At 12 hours after injection, which is the time point before DC migration to TDLNs or MEDI9197-mediated tumor apoptosis occurred, the mcMEDI group showed significantly increased frequencies of activated DCs (CD86+) and T cell subpopulations (CD69+) in the tumor tissue." (PMID 35579961, 2022). "Meanwhile, Cal/ICG@MPs significantly promoted DC maturation and tumor infiltration of CD8+ T cells, activated CD8+CD69+ T, CD8+IFN-γ+ T and CD8+ IL-2+ T cells, while decreased the ratios of Tregs and PMN-MDSCs in the contralateral tumors upon 808 nm laser irradiation." (PMID 35589680, 2022). "However, tumor-infiltrating CD4+ and CD8+ T cells showed much higher percentages of CD69, CCR5, and PDCD1 expression when compared with circulating T cells." (PMID 36301668, 2022). "When the immunophenotypes of the tumor samples were compared with the blood samples, statistically significant differences in the incidences of the CD3+ CD69+, CD4+ CD69+, and CD8+ CD69+ T cells in the tumor samples were 7.83, 9.67, and 10.5 times higher, respectively." (PMID 35158748, 2022). "The results revealed that the proportion of CD4+CXCR5+CD69+ cells in peripheral blood CD4+ T cells was independent of tumor location in OS patients." (PMID 35081874, 2022). "The role of CD69 has also been studied in tumour immunology where it has been identified as a negative regulator of the anti-tumour responses." (PMID 35930205, 2022). "Tumour infiltrating T cells did not express significant levels of T cell activation markers CD69 or CD25, or PD-1." (PMID 36405739, 2022). "Importantly, the majority of cells in cluster 5 were from P-LN and tumor 3, and they exhibited high expression of GNLY, CD69, and GZMA, indicating that they were closely related to immune cells." (PMID 36569924, 2022).
tumor (continued). "Interestingly, α1 demonstrated significant changes already at an early stage of tumor development (“Small tumor” group), which correlates with flow cytometry data on IFNγ production and the expression of CD25 and CD69." (PMID 36555468, 2022). "In contrast, MNK inhibitors did not affect the expression of PD-1, Prf1, or CD69 in CD8+ T cells isolated from the spleens of tumor-bearing mice treated with MNK inhibitors in vivo." (PMID 35380995, 2022). "The expression levels of CD69, IL7R, and PTPRC decreased with the progression of tumor stages." (PMID 36032150, 2022). "In support of that, we showed that, contrarily to terminally exhausted CD8 T cells, tumor-infiltrating exhausted CD4 T cells expressed only CD69, but no other Trm markers." (PMID 35954341, 2022). "Moreover, outside of the tumor, splenic CD8 T cells from lean and obese mice secreted similar levels of IFN-γ, TNF, and GzmB and expressed similar levels of CD69, CD44, CD36, Eomes, and T-bet." (PMID 35103755, 2022). "CD69 upregulation could induce LUAD cell apoptosis and inhibit tumor proliferation, invasion, and metastasis, thus suggesting a good prognosis." (PMID 35480896, 2022). "This analysis found that CD69 mRNA levels positively correlated with immune cell infiltration levels in most tumors, and that SBK1 mRNA levels negatively correlated with tumor infiltration by most immune cells." (PMID 36045683, 2022). "In the presence of autologous tumor cell membranes (TM), CD4+ and CD8+ T cells activated by FO or the crude lysates from FOLactis significantly had at least about a three-fold increase in surface expressions of CD69 and CD25 compared with the TM group." (PMID 36463242, 2022). "CD69, when expressed independently from CD103, is also a marker of intermediate tumor residency." (PMID 36003398, 2022). "This indicates that the OIP5-AS1-PTPRC/IL7R/CD69 and MALAT1-IL7R/CD69 axes in SKCM may affect the tumor immune microenvironment, leading to SKCM progression." (PMID 36032150, 2022). "In the murine tumor TIL therapy model, CD8+CD39-CD69- T cells could significantly suppress the tumor growth and prolong the survival of the mice to provide potential cure comparing to CD8+CD39+CD69+ T cells." (PMID 34332618, 2021). "The higher expression of CD69 and lower CD62L in patients indicate that these ILCs may correspond to recirculating tumor-exposed ILCs." (PMID 33810032, 2021). "While putative tumor-specific CD103+CD39+CD8+ TILs expressed lower CD69 (early activation marker) and higher PD-1 (extended activation/exhaustion marker) than colonic counterparts, the latter had instead higher CD69 and lower PD-1 levels." (PMID 34680397, 2021). "Tumor TRM share many surface molecules including CD69, CD103 and CD49a with pathogen-specific TRM, although their expression may vary between TRM in different tumor types." (PMID 34571883, 2021). "Correlation analyses showed that associations between CD80 on APC subsets vs. CD69 on T cell subsets defined by CD103 and CD39 were generally negative in the tumor and colon." (PMID 34680397, 2021). "The majority of Tag-Th1 cells in the tumor and PLN expressed the lymphocyte activation-associated membranous antigen CD69 independent of TBI, were further classified as effector memory T cells (CD44+CD62L-) and stained positive for the immune checkpoint PD-1." (PMID 34335959, 2021). "Consistent with tumor antigen exposure, we observed increased frequencies of in vivo-stimulated MM CD4+CD69+ T cells, although exhibiting lower potential to respond to further in vitro polyclonal stimulation, thus indicating a dysfunctional phenotype of PB CD4+ T cells." (PMID 34502204, 2021). "CD69 has also been shown to be upregulated only when NK cells are cocultured with tumor cells, and therefore we did not measure this marker in PBMCs alone." (PMID 33777767, 2021).
tumor (continued). "SKW-3 cells expressing the OSR11-2, but not the OSR11-1 chimera, increased the expression of CD69 on co-culture with Pt38 organoids, demonstrating that only one of the two α/β pairs was functional in recognizing antigens on Pt38 tumor cells." (PMID 34789550, 2021). "During tumorigenesis, CD69+CD8+/CD103+CD8+/CD49a+CD8+ T lymphocytes are highly activated, showing better effector function than traditional CD8+ T cells, and are able to control tumor growth." (PMID 35096624, 2021). "For example, activated CDC1 in tumor, but not colon, seem to confer CD69 downregulation on co-residing CD8+CD103+ TRMs." (PMID 34680397, 2021). "In addition, Met@Man-MPs markedly increased the numbers of CD8+ T, CD8+CD69+ T, and CD8+IFN-γ+ T cells in tumor tissues by flow cytometry." (PMID 33469052, 2021). "Upregulated expression of the CD8 T and NK cell activation marker CD69 was also detected within the non-irradiated left tumor." (PMID 34725216, 2021). "Mechanistically, tumour αV regulates CD8 T cell recruitment, induces CD103 expression on activated CD8+ T cells and promotes their differentiation to granzyme B-producing CD103+CD69+ resident memory T cells via autocrine TGF-β signalling." (PMID 34471106, 2021). "99LN‐BrM tumor cells alone did not significantly change T‐cell activity based on CD69, IFNγ, and Gzmb protein level." (PMID 33755340, 2021). "However, during tumor progression, lymphocytes were damaged in tumor microenvironment, and tumor infiltrating lymphocytes (TILs) with CD103+CD8+CD69+ were important for eliminating of tumor cells." (PMID 34633989, 2021). "Moreover, A2-CAR Jurkat T cells upregulated CD69 and CD25 expression specifically when co-cultured with irradiated HLA-A2+ K562 tumor cells, suggesting that the grafted A2-CAR is able to activate T-cell signaling in response to HLA-A2." (PMID 34616392, 2021). "Additionally, the DP T cell subset in the tumour, which comprised primarily of TEM and CD69-expressing cells, contained cells with high levels of granzyme B, suggesting that TRM-like DP T cells also have cytotoxic properties." (PMID 32439888, 2020). "A higher level of CD69-positive cells was observed in both types of CAR T cells compared to non-transduced T cells in response to PC-3 tumor cells." (PMID 32698361, 2020). "The attenuation of tumor progression in CD69 knockout mice was related to the increased levels of tumor infiltrating T cells and the decreased levels of CD8 T-cell exhaustion, and anti-CD69 antibody treatment enhanced the anti-tumor activity." (PMID 32849474, 2020). "In fact, IL-33 can directly activate human and mouse eosinophils by up-regulating activation markers (i.e. CD69), adhesion molecules (i.e., ICAM-1 and CD11b/CD18), and the degranulation markers CD63 and CD107a, resulting in the killing of several tumor cell types." (PMID 33329534, 2020). "On the other hand, the C1 (CD69+ T cell) (ave.cor = − 0.164) and C4 (B cell) (ave.cor = − 0.174) expressing genes are correlated with favorable prognosis of NSCLC, implying possible tumor-suppressive functions of these cells." (PMID 32580738, 2020). "However, they characterized CD69 and CD25 expression patterns on the surface of tumor-specific T-cells, which are markers of activation." (PMID 32582722, 2020). "These tumor-infiltrating cells present lower effector function than those in non-tumor tissues and a reduced expression of CD69, DNAM-1 and NKG2D." (PMID 32764229, 2020). "CD8+ TRM cells are identified by the co‐expression of CD69+CD103+,99, 100 and they may prevent the development of clinically relevant cancer through tumor immune equilibrium and CD103‐enhanced tumor cell killing." (PMID 32994997, 2020). "While CD69 and CD103 are commonly used to identify TRM cells, these markers might also be upregulated on activated tumor-infiltrating T-cell subsets in the context of tumors." (PMID 32695313, 2020).
tumor (continued). "Inhibition of the PI3K signaling pathway by BKM120 inhibited tumor growth and lung metastasis by enhancing anti-tumor immunity by decreasing the number of CD4+ TILs, increasing the number of activated CD4+CD69+ T cells, and decreasing the number of CD20+ B cells." (PMID 32570871, 2020). "Consistent with the results obtained in vivo with the EVs-ARG1 in the adoptive transfer model in non-tumor settings, ID8-ARG1 bearing-mice had a significantly reduced percentage of activated CD69-positive CD4+ and CD8+ T-cells in the peritoneal cavity relative to mice bearing control tumor cells." (PMID 31278254, 2019). "Adoptively transferred, tumour-specific CD8+ T cells were activated and recruited to the site of tumour inoculation and gave rise to TRM cells expressing the canonical tissue-retentive molecules CD69 and CD103." (PMID 31225511, 2019). "Significantly higher CD69 levels, in both CD4+ and CD8+ cell populations, were observed in the HPK1 KD group in comparison with WT group, indicating that HPK1 KD leads to augmentation of T cell activation in the tumor bearing mice." (PMID 30913212, 2019). "Since L-selectin knockout T cells do not control tumor growth yet CD69 is upregulated in secondary lymphoid organs, it is unlikely to be related to events in lymph nodes or spleen." (PMID 31249570, 2019). "Whether CD69 expression is maintained on activated F5LΔP tumor infiltrating T cells throughout the course of the therapy and increases the number of CD8+ tumor infiltrating T cells due to retention will be interesting to address." (PMID 31249570, 2019). "An upregulation of CD69 activation marker occurs for both CD4+ and CD8+ (Fig. 5AII) UniCAR T cells in a strict tumor-specific and TM-dependent manner, while the activation level of UniCAR T cells redirected by the His-tagged or un-tagged TM was indistinguishable." (PMID 31332252, 2019). "In both of direct and transwell co-culture systems, IFN-γ secretion and CD69 expression, an activation marker were highest in Jurkat cells without tumor cell co-culture (“Jurkat only”)." (PMID 31718692, 2019). "Neither the genotype nor the treatment had an influence on CD4+ and CD8+ T cell frequencies in spleen and tumor; however, poly(I:C)c failed to induce CD69 expression in T cells of Ifnar1−/− mice." (PMID 31694706, 2019). "Interestingly, we found that T-cell activation, as documented by up-regulation of CD25, CD137, and CD69, by the TRAIL-R2/CD3 scDb was strictly dependent on the presence of TRAIL-R2+ tumor cells in the experimental assay." (PMID 31708930, 2019). "Similarly, in the experiments with CEA‐positive tumor cells as target cells, the expression levels of CD25 and CD69 on CEA‐CAR‐T cells surface under CEA‐CAR‐T cells in combination with rhIL‐12 treatment were significantly higher than CEA‐CAR‐T cell treatment." (PMID 31237116, 2019). "Moreover, CD4 T cells derived from the tumor site of VTA-activated mice manifested elevated levels of the activation marker, CD69 (P < 0.001)." (PMID 30006573, 2018). "Furthermore, this study also showed decreased expression of the lymphocyte proliferation marker CD69, the homing receptors CXCR3 and CCR5, and the NKRs NKG2D and DNAM-1 on NKT-like cells in tumor tissue compared with non-tumor tissue." (PMID 29535734, 2018). "Comparing tumour infiltrating ILC populations with circulating ILC, showed that ILC populations have an activated phenotype in tumour tissue with higher expression of MHC-II, KLRG1, CD69 and CD44." (PMID 29587679, 2018). "While CD69+ T cells were virtually absent in peripheral blood, they dominated in the lung and tumor." (PMID 30505306, 2018). "Exposure of CD3 cells to the EpCAM BiTE in the absence of tumour cells gave a very modest increase in CD69 and CD25, and this indicates that antibody‐mediated clustering of CD3 is essential for full activation by this anti‐CD3 binding." (PMID 28634161, 2017).